TFE3 (transcription factor binding to IGHM enhancer 3)
Diseases named in the same sentence as TFE3 in open-access papers (continued):
Sharing a sentence is not in itself a finding about the gene and the disease.
PEComas (71 papers, 2014 to 2026). "Many liver PEComas exhibit different biological behavior, especially in cases of mutations such as TFE3 rearrangement." (PMID 40723161, 2025). "PEComas with TSC1/2 mutations or TFE3 rearrangements respond to mTORC1 inhibition, while IMTs harboring ALK, RET, PDGFRB, or NTRK rearrangements demonstrate marked responses to ALK or TRK inhibitors." (PMID 41463261, 2025). "In contrast, PEComas with TFE3 rearrangements, associated with MET pathway activation, tend to exhibit lower response rates to mTOR inhibitors." (PMID 40647483, 2025). "There are some PEComas associated to tuberous sclerosis because of transcription factor E3 (TFE3) gene rearrangements." (PMID 41180120, 2025). "TFE3 translocation-associated PEComas have uniform epithelioid cells with either purely clear or clear-to-eosinophilic cytoplasm." (PMID 39064514, 2024). "It is recommended to detect the expression of TFE-3 protein, because TFE3-positive PEComas are associated with poor prognosis." (PMID 39220650, 2024). "Previous reports have shown that PEComas associated with TFE3 gene rearrangements form a distinct molecular subtype which tends to have a more aggressive behavior." (PMID 37448552, 2023). "In contrast to conventional PEComas, TFE3-rearranged PEComas were shown to lack TSC2 inactivating mutations." (PMID 37470853, 2023). "Recently, it was suggested that TFE3 translocation-associated PEComas of the gynecologic tract represent a distinct form of this tumor." (PMID 36647157, 2023). "Both morphology and immunophenotype of the tumor were consistent with those TFE3 translocation-associated PEComas described previously." (PMID 36647157, 2023). "Perivascular epithelioid cell tumors (PEComas) are rare mesenchymal neoplasms characterized by myomelanocytic differentiation and dichotomic molecular pathogenesis (mTOR-activating mutations versus TFE3 gene rearrangements)." (PMID 41790187, 2026). "Like tRCC, TFE3-fusion associated PEComas also tend to arise in young adults, are more common in females and may be associated with prior chemotherapy." (PMID 41044182, 2025). "Therefore, the immunoprofile of renal and extrarenal TFE3-rearranged PEComas overlaps, but it slightly differs from PEComas related to TSC1/TSC2 mutations, in which the expression of muscle markers, particularly actin, is more frequently observed." (PMID 39410016, 2024). "A subset of PEComas, the TFE3 translocation-associated PEComa, lack TSC mutation which may lead to hypothetical ineffectiveness of mTOR inhibitor therapy." (PMID 38664269, 2024). "We detected focally TFE3 positivity as per the immunohistochemical protocol (an automatic protocol) that may reveal TFE3 translocation-associated PEComas." (PMID 36367123, 2023). "This case suggests that targeting the VEGF/VEGFR signaling pathway may be an essential new therapeutic choice for TFE3-associated malignant PEComas." (PMID 33330059, 2020). "Also, TFE3 rearrangements have been found to be mutually exclusive with TSC2 mutations in PEComas which has been hypothesized to be responsible for the worse prognosis of these patients." (PMID 37448552, 2023). "TFE3-translocated PEComas are less responsive to mTOR inhibitors, and the low response rate is associated with MET pathway activation, which is one of the mechanisms of mTOR inhibitor resistance." (PMID 40989692, 2025). "These TFE3-rearranged PEComas predominantly consist of alveolar and epithelioid cells with low immunoreactivity for muscle markers and high immunoreactivity for TFE3 (3+)." (PMID 40989692, 2025). "The SFPQ/TFE3 gene fusion is also present in perivascular epithelioid cell tumours (PEComas) and melanotic Xp11 translocation renal cancers." (PMID 40276932, 2025).
PEComas (continued). "Approximately 15% of the PEComas demonstrate nuclear staining for TFE3, particularly in the TFE3-rearranged subtypes." (PMID 40002892, 2025). "Aberrant immunoreactivity for TFE3 protein has been previously observed in the vast majority of PEComas; subsequent analysis of the gene status revealed a distinct subset of PEComa cases with TFE3 gene fusions." (PMID 40900800, 2025). "While studies on the pathogenesis of PEComas have largely established the role of the 2 main genomic drivers (TSC1/2 loss and TFE3 fusions), recent work has further characterized their interdependence." (PMID 41044182, 2025). "These TFE3-rearranged PEComas tend to occur in younger patients and often exhibit epithelioid morphology, high nuclear grade, and a more aggressive clinical course." (PMID 41463261, 2025). "(c) Is there any point in currently classifying mesenchymal renal neoplasms carrying TFE3 rearrangements as PEComas?" (PMID 39410016, 2024). "Renal TFE3-rearranged PEComas show a female predominance (17 females versus 11 males, 60% versus 40%) and occur in young patients (10 cases in the second decade, 37%)." (PMID 39410016, 2024). "In 2009, a subset of PEComas carrying TFE3 gene fusions, expressing melanogenesis markers, and rarely showing immunoreactivity for muscle markers, was identified in young patients without TSC." (PMID 39410016, 2024). "The immunoreactivity of HMB45, SMA, Melan-A, Vimentin, and Desmin in PEComas has been extensively discussed, along with the progression of TFE3 staining positivity in PEComas." (PMID 38689335, 2024). "Wang and colleagues highlighted melanin pigment as a distinctive characteristic between TFE3-rearranged PEComas and TSC-related PEComas, especially in tumors arising in the kidney." (PMID 39410016, 2024). "ASPSCR1-TFE3, along with other TFE3 fusion proteins, also contributes to the development of a subset of perivascular epithelioid cell tumors (PEComas)." (PMID 38386415, 2024). "The different percentages of the expression of the melanogenesis marker HMB45 explain why melanin pigment is identified more frequently in renal TFE3-rearranged PEComas (80%) than in TFE3-rearranged renal cell carcinoma of the kidney (33%)." (PMID 39410016, 2024). "The immunohistochemical analysis of renal TFE3-rearranged PEComas consistently shows a robust expression of cathepsin K (99%) and melanogenesis markers (HMB45 91% and MART1/MELAN A 80%) along with negativity for PAX8, cytokeratins, and S100." (PMID 39410016, 2024). "Regarding TFE3-rearranged PEComas, 74% and 49% of the renal and extrarenal tumors carry SFPQ/PSF::TFE3 and NONO::TFE3 rearrangements, respectively." (PMID 39410016, 2024). "The presence of melanin pigment in some renal TFE3-rearranged PEComas has been considered a distinctive feature from PEComas carrying TSC1/2 mutations, leading some authors to propose reclassifying them as “melanotic Xp11 neoplasms”." (PMID 39410016, 2024). "We also identified high levels of TRIM63 RNA-ISH staining in three of five (60%) PEComas, a subset of which are known to harbor TFE3 fusions." (PMID 38393424, 2024). "Tumors with high expression of TFE3 were classified as PEComas with malignant potential according to Folpe’s classification." (PMID 37470853, 2023). "Approximately 40 cases of PEComas of the urinary bladder and 4 cases of PEComas of the prostate have been reported in the literature; only 9 cases of bladder PEComas and 1 case of prostatic PEComas with TFE3 rearrangement have been described in the literature." (PMID 36647137, 2023). "In contrast, a distinct small subset of PEComas harboring rearrangements of the TFE3(Xp11) gene locus has been identified." (PMID 37470853, 2023). "The TFE3-rearranged PEComas harbor TFE3 gene fusions, which correlate with a strong nuclear immunoreactivity for TFE3; approximately 15% cases show strong nuclear staining for TFE3." (PMID 37470853, 2023).
PEComas (continued). "Although most PEComas harbor loss-of-function TSC1/TSC2 mutations, a small subset of PEComas show rearrangement of the TFE3 gene." (PMID 36647157, 2023). "TFE3-related PEComas share similar histopathological features, such as epithelioid appearances, alveolar or nested growing patterns, and low nuclear atypia." (PMID 36367123, 2023). "These TFE3-rearranged PEComas tend to occur in younger patients and display strong nuclear TFE3 expression." (PMID 37041531, 2023). "Tumors with high expression of TFE3 (2 + or higher) were classified as PEComas with malignant potential according to Folpe’s classification." (PMID 37470853, 2023). "TFE3 overexpression highlighted a subgroup of PEComas with worse prognosis and more aggressive behavior." (PMID 37448552, 2023). "The gene rearrangement of the MIT/TFE family of transcription factors member TFE3 (chromosome Xp11.23) has been reported in a small minority of PEComas, including SFPQ/PSF-TFE3 fusion and DVL2-TFE3 fusion." (PMID 36367123, 2023). "Around 20% of PEComas were found to be positive for TFE3 nuclear staining, among which many of them harbour TFE3 gene rearrangement." (PMID 35232443, 2022). "This case differed from otherreported TFE3-rearranged PEComas in that immunostaining showed positivityfor desmin and TFE3." (PMID 35699228, 2022). "Regarding molecular characteristics, PEComas are characterized by mutations leading to mTOR pathway activation, such as TSC1 or TSC2 bi-allelic inactivation, TFE3 gene fusion and FLCN truncating mutations." (PMID 34680376, 2021). "Combined RNA sequencing and fluorescence in situ hybridization [FISH] of 38 PEComas of different sites detected 9 (23%) TFE3 gene-rearranged tumors." (PMID 32685651, 2020). "Recently, a subgroup of PEComas harboring TFE3 (Transcription Factor E3) rearrangements and presenting with a distinctive morphology has been identified." (PMID 33180365, 2020). "The PEComas of this group exhibit distinctive morphological features known from other TFE3 rearranged tumors such as Xp11-translocation renal cell cancer and alveolar soft part sarcoma, including an alveolar growth pattern and an epithelioid cytomorphology." (PMID 31309284, 2020). "Recently, a distinct subset of PEComas with transcription factor E3 (TFE3) rearrangement, unique morphology, and characteristic immunophenotype has been revealed." (PMID 31103952, 2019). "PEComas are composed entirely of clear epithelioid cells with nested or alveolar-architecture, round to ovoid nuclei, strong expression of TFE3 and HMB45, and minimal expression of muscle markers." (PMID 31103952, 2019). "TFE3 rearrangements are also present in alveolar soft part sarcoma, certain pediatric renal cancers and a subset of PEComas." (PMID 24986479, 2014). "TFE3-rearranged PEComas that exhibit strong TFE positivity and minimal desmin and actin positivity have also recently been described." (PMID 24735727, 2014). "Overexpression of TFE3 mediates expression of cathepsin K, which may represent an IHC marker useful in the identification of TFE3-altered PEComas." (PMID 40900800, 2025). "Here, we describe a transgenic mouse model of renal tumorigenesis induced by SFPQ-TFE3 expression, the most common TFE3 gene fusion seen in human PEComas and their melanotic variants, and the last of the three most common tRCC fusions that has yet to be modeled in mice." (PMID 41044182, 2025). "In general, fusion-driven neoplasms, including JAZF1-rearranged LG-ESS, YWHAE- or BCOR-altered HG-ESS, ALK- or NTRK-rearranged IMTs, and TFE3-rearranged PEComas, harbor early, lineage-defining genomic events that are consistently detectable across disease stages." (PMID 41463261, 2025). "A smaller subset of PEComas harbors rearrangements involving TFE3 or RAD51B." (PMID 40647483, 2025).
PEComas (continued). "Future work will further probe the mechanism of epithelial lineage plasticity induced by TFE3-fusions and continue to refine the conditions in which mTOR kinase inhibition may have therapeutic efficacy in human fusion-driven tRCC and PEComas." (PMID 41044182, 2025). "Rearrangement or amplification of the TFE3 gene has been reported in approximately 30% of PEComas in the literature, so immunohistochemical examination may detect positive TFE3 protein expression." (PMID 40989692, 2025). "Furthermore, melanin pigment deposits have been identified in about half of renal TFE3-rearranged PEComas." (PMID 39410016, 2024). "A subset of PEComas is driven by TFE3 fusions with corresponding nuclear TFE3 expression." (PMID 37131332, 2024). "c-MET inhibitors may be more effective in TFE3-altered PEComas because TFE3 fusions increase MET signaling through transcriptional up-regulation." (PMID 39026968, 2024). "TFE3-rearranged PEComas were identified as a distinctive subset of PEComas." (PMID 39759135, 2024). "The prior literature also highlights TFE3 (transcription factor E3)-rearranged PEComas with a lack of TSC1/2-inactivating mutations." (PMID 38535035, 2024). "TSC alterations/TFE3 fusions are characteristic of uterine PEComas." (PMID 39759135, 2024). "Nevertheless, in this study, although they recognized that extensively melanotic pigmented TFE3-rearranged PEComas, originally described as “melanotic Xp11 translocation renal cancer”, exist on the spectrum of these tumors, they avoided including this characteristic in the name." (PMID 39410016, 2024). "For this reason, further studies will be needed to confirm the prognostic role of TFE3 overexpression in PEComas, and to define the molecular basis for TFE3 overactivity in PEComas and how this could be exploited therapeutically." (PMID 37448552, 2023). "In addition, regardless of the rearrangement of the TFE3 gene, 29% to 38% of PEComas can show positive findings for the TFE3 transcription factor." (PMID 37565900, 2023). "Bone and soft tissue PEComas are more likely to result in TFE3 rearrangements." (PMID 37470853, 2023). "Our results also suggest that mechanisms different from gene fusion might be responsible for the increased activity of TFE3 in PEComas." (PMID 37448552, 2023). "Although most patients have sporadic PEComas, a subset may be associated with the inactivation of TSC1 or TSC2 genes and the occurrence of TFE3 gene fusions." (PMID 36367123, 2023). "Bone and soft tissue PEComas may have a higher malignancy potential than other visceral PEComas and are more likely to develop as TFE3-rearranged PEComas." (PMID 37470853, 2023). "In addition, tumors with high expression of TFE3 (2 or higher) (cases 2–8) were classified as PEComas with malignant potential according to Folpe’s classification." (PMID 37470853, 2023). "Our study shows that PEComas of the bone and soft tissues are more likely to develop into TFE3-rearranged PEComas, which may be useful for developing future treatment strategies." (PMID 37470853, 2023). "A subset of PEComas demonstrate rearrangements involving the TFE3 (Xp11) locus." (PMID 36647137, 2023). "c-MET inhibitors could be more efficient in TFE3-altered PEComas, since TFE3 fusions activate MET signaling by transcriptional up-regulation." (PMID 34680376, 2021). "Finally, rearrangement of TFE3 is also characteristic of a subset of PEComas, for which TFE3 immunohistochemistry can also be used." (PMID 33921435, 2021). "Overexpression of TFE3, member of the microphthalmia transcription factors family (MiTF), mediates the expression of cathepsin-K, which might be another IHC marker helpful to diagnose TFE3-altered PEComas." (PMID 34680376, 2021). "Even though access to molecular biology has increased since previous reviews, very few cases reported the search for a TFE3 translocation, a TSC1 or TSC2 loss of function mutations or even no FCLN mutation, considered to be the more recent genomic alterations described in PEComas." (PMID 34680376, 2021).
PEComas (continued). "Hence, IHC should be performed to identify positive PEComas before looking for a TFE3 gene rearrangement, since some of these PEComas will have a TFE3 gene fusion." (PMID 34680376, 2021). "TFE3 is positive in a distinct subset of PEComas that harbor TFE3 gene fusions." (PMID 32867125, 2020). "Additionally, a distinct small subset of PEComas harboring rearrangements of the TFE3(Xp11) gene locus have been identified." (PMID 31309284, 2020). "Additionally, a distinct small subset of PEComas harboring rearrangements of the TFE3 (Xp11) gene locus has been identified." (PMID 31309284, 2020). "However, accumulating evidence suggests that PEComas with TFE3 rearrangement have relatively aggressive clinical behaviors." (PMID 31103952, 2019). "Recently, a distinct subset of PEComas was reported to harbor a TFE3 gene fusion." (PMID 27871249, 2016). "Besides Xp11 translocation RCC and ASPS, perivascular epithelioid cell tumors (PEComas) have also shown immunoreactivity for TFE3." (PMID 26415891, 2015). "Recently, several reports described TFE3 expression in PEComas." (PMID 24410788, 2014). "Two cases with malignant TFE3-rearranged PEComa showed treatment response with the antivascular endothelial growth factor (VEGF) receptor tyrosine kinase inhibitor apatinib, suggesting that VEGF signaling may also be implicated in TFE3-associated PEComas." (PMID 40900800, 2025). "Additionally, a subset of PEComas exhibit TFE3 gene rearrangements." (PMID 40002892, 2025). "Therefore, we question whether this characteristic is sufficient to change the name of TFE3-rearranged PEComas at this time." (PMID 39410016, 2024). "Also in PEComas, the TFE3 fusions include its DNA binding domain and nuclear localization signal." (PMID 38611033, 2024). "PEComas with TFE3 fusions are enriched for epithelioid morphology (“epithelioid PEComa”) and alveolar architecture, representing substantial morphologic overlap with ASPS." (PMID 38393424, 2024). "Therefore, evaluation of TFE3 gene expression in PEComas could recognize this entity and aid therapeutic decisions." (PMID 31103952, 2019). "According to previous descriptions of immunohistochemical markers expression in PEComas arising at different sites, a second line of IHC was hence performed using antibodies against microphthalmia transcription factor (MiTF), transcription factor E3 (TFE3), and muscle marker Calponin." (PMID 26925281, 2016). "Furthermore, these FISH assays can be used as an adjunctive method to improve the accuracy of diagnosis for Xp11.2 tRCC, ASPS, PEComas, and other neoplasms that are characterized by a rearrangement of the TFE3 gene and the presence of the ASPL-TFE3 fusion gene." (PMID 25984679, 2015). "Therefore, c-MET inhibitors may be more effective in TFE3-altered PEComas." (PMID 40989692, 2025). "For instance, while PEComas can share some histological features and may rarely harbor TFE3 rearrangements (often with different fusion partners), and RCC variants can exhibit clear cells and vascularity, the presence of the definitive ASPSCR1-TFE3 fusion is pathognomonic for ASPS." (PMID 41446840, 2025). "Explaining the mutual exclusivity between TSC1/2 inactivation and MiT/TFE gene rearrangements in PEComas, we and others have previously shown that mTORC1 activation leads to constitutive activation of TFEB and TFE3 through FLCN inactivation." (PMID 41044182, 2025). "Recent studies have revealed the presence of TFE3 gene rearrangements in 23% of PEComas, which involve the formation of gene fusions such as SFPQ/PSF::TFE3 and DVL2::TFE3." (PMID 38291475, 2024). "PEComas are most commonly found in females and often show either TSC1 or TSC2 alterations, which result in the activation of the mTOR pathway, or TFE3 fusions." (PMID 37041531, 2023). "Two major molecular subgroups have recently been identified for PEComas: those with TSC1 or TSC2 alterations and those with TFE3 fusions." (PMID 37041531, 2023).